LHFPL1 (LHFPL tetraspan subfamily member 1)
Tractability: Antibody: UniProt predicts a signal peptide or a membrane-spanning region.
Gene: Protein-coding gene on chromosome X (112,625,372 to 112,680,180, reverse strand). Ensembl gene ENSG00000182508.
Subcellular location: Membrane
Gene Ontology:
Molecular function: protein binding
Cellular component: membrane
Homologues: Orthologues: chimpanzee LHFPL1 (99% identical), macaque LHFPL1 (99% identical), pig LHFPL1 (97% identical), guinea pig LHFPL1 (96% identical), rat Lhfpl1 (95% identical), mouse Lhfpl1 (95% identical), rabbit LHFPL1 (81% identical), dog LHFPL1 (78% identical), tropical clawed frog lhfpl1 (65% identical). Paralogues in human: LHFPL6 (57% identical), LHFPL2 (26% identical), LHFPL3 (24% identical), LHFPL4 (23% identical), LHFPL7 (22% identical), LHFPL5 (20% identical).
Diseases named in the same sentence as LHFPL1 in open-access papers:
LHFPL1 is named in the same sentence as 1 disease in open-access papers, as found by Europe PMC text mining. Sharing a sentence is not in itself a finding about the gene and the disease. The quoted sentences say what the papers report.
deafness (1 paper, 2022). An inherited or acquired condition characterized by the complete loss of the ability to hear from one or both ears. "Lhfpl1 belong to a family of LHFP genes known to be involved in deafness if they are mutated." (PMID 36386828, 2022).